GZMB (granzyme B)
Diseases named in the same sentence as GZMB in open-access papers (continued):
Sharing a sentence is not in itself a finding about the gene and the disease.
atherosclerosis (24 papers, 2011 to 2025). A disease characterized by the build-up of fatty material and calcium deposition in the arterial wall resulting in partial or complete occlusion of the arterial lumen. "In many other inflammatory diseases, such as rheumatoid arthritis, atherosclerosis and infections, an increased level of extracellular granzyme B has been observed, which was associated with inflammatory mediators and disease exacerbation." (PMID 37374379, 2023). "Particularly relevant to our findings, IL1b mRNA levels are decreased in perforin or granzyme B deficient mice compared to WT mice in a mouse model of atherosclerosis." (PMID 28192528, 2017). "B cells, T cells (including clonally expanded CD4+ cells with heightened proinflammatory and CD8+ cells with cytotoxic properties), granzyme B, TNF-α, IL-6, and TLR 2 and 4 all contributed to the inflammatory processes underlying atherosclerosis." (PMID 40046046, 2025). "In the progression of atherosclerosis, GzmB is prevalently found in unstable atherosclerotic plaques." (PMID 38966643, 2024). "For example, macrophages have been shown to express granzyme B in the lesion areas of atherosclerosis and rheumatoid arthritis." (PMID 39684816, 2024). "The accumulation of NK cells in atherosclerotic lesions leads to the expansion of necrotic cores and accelerates atherosclerosis through the release of perforin, granzyme B, and pro-inflammation factor IFN-γ." (PMID 35281895, 2022). "For example, Chamberlain, C., and Granville, D., suggested that in atherosclerosis, immune-mediated cellular apoptosis plays a crucial role, and GZMB interferes there." (PMID 36072953, 2022). "Granzyme B and perforin release by the activated T cells could also contribute to endothelial cell damage and death–indeed, in an adoptive transfer mouse model of atherosclerosis, transfer of CD8 T cells deficient in granzyme B, perforin, or TNF attenuated atherosclerotic lesions." (PMID 32976527, 2020). "Although these results were unexpected, a previous study has shown that macrophages express granzyme B in human inflammatory diseases such as atherosclerosis and rheumatoid arthritis." (PMID 30044851, 2018). "To further investigate the role of GzmB and Prf1 in the development of atherosclerosis in ApoE KO mice, we generated GzmB/ApoE DKO and Prf1/ApoE DKO mice." (PMID 24205352, 2013). "In this study, we investigated the role of both GzmB and Prf1 in the pathogenesis of atherosclerosis." (PMID 24205352, 2013). "The present study suggests that Prf1 and GzmB exert unique roles in the onset and progression of atherosclerosis." (PMID 24205352, 2013). "GzmB-mediated apoptosis has therefore been suggested to play a pathological role in atherosclerosis." (PMID 24205352, 2013). "The data suggests that GzmB and Prf1exert differential roles in atherosclerosis, influencing plaque composition and plaque development, respectively." (PMID 24205352, 2013). "In conclusion, both Prf1 and GzmB contribute to the pathogenesis of atherosclerosis in ApoE KO mice." (PMID 24205352, 2013). "With the evidence from both aspects of GZMB, we may pursue that GZMB may be involved in forming atherosclerosis in a group or subgroup of patients with immunological disorders." (PMID 36072953, 2022). "CD8+T cells promote atherosclerosis by perforin- and granzyme B- mediated cytotoxic mechanisms, as supported by their failure in this action following adoptive transfer of CD8+T cells deficient in perforin and granzyme B." (PMID 32849502, 2020). "As such, GzmB-mediated ECM degradation may play a more profound role in advanced atherosclerosis and plaque rupture compared to the early stages of the disease." (PMID 24205352, 2013). "Other studies have also investigated the role of GzmB and Prf1 in atherosclerosis.One study by Viswanathanet al showed that GzmB/ApoE DKO mice exhibit a trend towards reduced plaque development compared to ApoE KO mice in a model of aortic allograft vasculopathy." (PMID 24205352, 2013).
atherosclerosis (continued). "Together these results suggest significant, yet separate roles for granzyme B and perforin in the pathogenesis of atherosclerosis that go beyond the traditional apoptotic pathway with additional implications in plaque development, stability and remodelling of extracellular matrix." (PMID 24205352, 2013). "Elevated levels of GZB were detected in the plasma of patients with atherosclerosis, with the highest levels detected in patients with unstable plaques, lending support to the hypothesis that granzyme B influences plaque instability." (PMID 24307760, 2013). "Therefore, GzmB and Sb9 could be effective modulators in the development and progression of atherosclerosis." (PMID 38966643, 2024). "Consequently, regulating GzmB through Sb9 could represent a novel therapeutic strategy for preventing cardiovascular diseases, such as atherosclerosis, plaque rupture, and ventricular remodeling after acute myocardial infarction (AMI)." (PMID 38966643, 2024). "In addition, by depleting NK cells by anti–GM1 antibodies or transferring NK cells in atherosclerosis-prone ApoE-deficient mice, NK cells were demonstrated to play a protective role in the development of atherosclerosis, possibly via secretion of the cytotoxic molecules perforin and granzyme B." (PMID 33717101, 2021). "It has been shown that overexpression of SLC4A10 leads to a reduction in the secretion of GZMB and IFN-γ, thereby attenuating the progression of atherosclerosis and facilitating the stable development of plaques." (PMID 40510365, 2025). "Although we did not observe a difference in Granzyme B production by stimulated NK cells comparing groups, we cannot rule out increased NK cytotoxicity, or increased target cell susceptibility, as a contributing factor promoting atherosclerosis in Cd47−/− mice." (PMID 31337788, 2019). "We also generated GzmB/ApoE double knockout (DKO) mice and Prf1/ApoE DKO mice to investigate the potential roles of these twoproteins in atherosclerosis." (PMID 24205352, 2013). "All of this indicates that IFN-γ and GZMB induce SMC apoptosis, promoting atherosclerosis." (PMID 40510365, 2025). "In summary, this study supports the fact that SLC4A10 weakens the toxic functions of CD8+ T cells in secreting IFN-γ and GZMB via the MAPK pathway, exerting a significant role in decelerating the development of atherosclerosis and facilitating plaque stability." (PMID 40510365, 2025). "The current study also provides evidence thatPrf1contributes to the incidence and development of atherosclerosis in the descending aorta through mechanisms that are independent of GzmB." (PMID 24205352, 2013). "Therefore, as many of these ECM proteinsare well-described GzmB substrates, it is possible that the role of GzmB in atherosclerosis pathogenesis is not limited exclusively to Prf1-dependant intracellular apoptosis, but could potentially include ECM remodelling events as well." (PMID 24205352, 2013).
ovarian carcinoma (22 papers, 2015 to 2025). A malignant neoplasm originating from the surface ovarian epithelium. "Of note, GZMB expression was significantly higher in ovarian cancer patients that were sensitive to chemotherapy." (PMID 40002821, 2025). "Under the limitation of the in vitro experiments, the fusion antibodies modestly enhanced granzyme B production from the activated T cells and showed trends in enhancing the anti-ovarian cancer activity of tumor-reactive T cells." (PMID 38140230, 2023). "Through miRNA, these lncRNAs are connected with PRGs such as IRF1, NOD1, GSDMC, NLRP1, PLCG1, GSDME and GZMB to construct a pyroptosis related ceRNA regulatory network in ovarian cancer." (PMID 37859811, 2023). "They showed enhancement trends for other effector T cell activities like granzyme B production and lysis of ovarian cancer cells when added to the activated T cells." (PMID 38140230, 2023). "The expression of GSDMD and GZMB were both significantly correlated with Pyrsig score (P = 0.018 and P = 0.034, respectively) in 65 ovarian cancer patients." (PMID 36707884, 2023). "Hsp22 correlated with Granzyme B in all three groups: ovarian cancer (tau = 0.7, p = 0.0007), endometrial cancer (tau = 0.6, p = 0.003), endometriosis (tau = 0.8, p = 0.001)." (PMID 31285463, 2019). "Hsp20 correlated with Granzyme B in all three groups: ovarian cancer (tau = 0.8, p = 0.0001), endometrial cancer (tau = 0.6, p = 0.028), endometriosis (tau = 0.8, p = 0.016)." (PMID 31285463, 2019). "NK cell performance of the cytotoxicity against target cells mainly depends on releasing effective molecules, perforin and granzyme B, so we further tested the expression of the two molecules in ovarian cancer tissues." (PMID 26497895, 2015). "Furthermore, the treatment effects of granzyme B-based cytolytic fusion proteins have been identified in various types of cancer including ovarian carcinoma." (PMID 34944392, 2021). "Alpha-B Crystallin correlated with Granzyme B in ovarian cancer group (tau = 0.6, p = 0.006)." (PMID 31285463, 2019). "Regarding peritoneal fluid samples, the highest expression level of Granzyme B was observed in patients with ovarian cancer (median: 198, IQR: 72–451 pg/mL), which was significantly higher compared to patients with endometrial cancer (median: 81, IQR: 19–141 pg/mL, p = 0.02)." (PMID 31285463, 2019). "IFN-γ was generated by NK cells, while IFN-γ again reacted on NK cells, which may enhance cell-mediated cytotoxicity by delivering perforin and granzyme B, and develop central biological role in killing ovarian cancer cells." (PMID 26497895, 2015). "We found that XBP1 was significantly correlated with key immunity-killing molecules, including FASL, PRF1, IFNG, GZMB, TNFa, and CD40L in ovarian cancer." (PMID 35991556, 2022). "NKT cells strongly expressed the GZMB, GZMA, GZMH, and PRF1 genes, indicating that they promoted tumor cytotoxicity in ovarian cancer." (PMID 35935940, 2022). "In ovarian carcinoma, the expression of APOBEC3G was positively correlated with T cell infiltration, expression of cytotoxic granzyme and perforin (GZMB and PRF1), and improved clinical outcome." (PMID 34307377, 2021). "To investigate the mechanisms of BiTEDs-mediated cytotoxicity, we evaluated intracellular granzyme-B and cytokine levels in T-cells cultured for 24 hours with MUC16pos ovarian cancer cells with or without BiTEDs." (PMID 33936101, 2021). "Given the enhanced secretion of granzyme B by T cells and the increased infiltration of T cells into ID8 ovarian tumors following treatment with compound 968, we conclude that compound 968 is an ideal partner to cooperate with immune checkpoint inhibitors in ovarian cancer." (PMID 34944392, 2021). "We show that surprisingly, overexpression of the Granzyme B (GZMB) inhibitor, protease inhibitor-9 (PI9), does not alter the cytotoxicity mediated by CD19-specific CAR T cells against either the leukemic cell line, NALM6; or the ovarian cancer cell line, SkOV3-CD19." (PMID 38307835, 2024).
rheumatoid arthritis (20 papers, 2012 to 2025). A chronic, systemic autoimmune disorder characterized by inflammation in the synovial membranes and articular surfaces. "Diseases with presumptive autoantigens cleaved by granzyme B include lupus erythematosus, rheumatoid arthritis, scleroderma, myositis, and Sjögren’s syndrome, of which more than 20 autoantigens have been identified." (PMID 38384322, 2023). "In an autoimmune condition such as rheumatoid arthritis, characterized by immune system attacking normal self-tissues, especially joints, GzmB may play a significant extracellular role, contributing to tissue damage." (PMID 38846935, 2024). "Serval studies have revealed that GzmB-producing regulatory B cells are decreased in peripheral blood of systemic lupus erythematosus (SLE), lupus nephritis, and rheumatoid arthritis (RA), which are closely associated with poor prognosis of these diseases." (PMID 36439094, 2022). "In contrast to rheumatoid arthritis, in which the CD8+ T cells had low levels of granzyme B and perforin, CD8+ T cells found in Lyme arthritis samples were characterized by elevated levels of these cytotoxic molecules." (PMID 40661371, 2025). "A population of CD8+ T cells marked by the strong expression of GZMK but relative absence of GZMB was identified (cluster 3), consistent with a phenotype previously recognized in LN kidneys and rheumatoid arthritis synovium." (PMID 35290245, 2022). "A previous study found that GZMB gene silencing acts to inhibit MAPK signaling pathway through regulating the expressions of inflammatory factors, thus relieving the injury brought by Rheumatoid arthritis." (PMID 34126969, 2021).
glioblastoma (19 papers, 2009 to 2026). The most malignant astrocytic tumor (WHO grade IV). "The granzyme B gene encodes the GZMB protein which is a serine protease belonging to the peptidase S1 family; over-expression of this serine protease has been previously shown to be associated with poor survival outcomes in patients with glioblastoma." (PMID 34643804, 2022). "Interferon-γ (IFNγ), tumor necrosis factor-α (TNFα), granzyme B, and IL-4 levels were significantly increased in iNKT cells stimulated with the α-GalCer-pulsed glioblastoma cell lines in a CD1d-dependent manner." (PMID 33128583, 2021). "At the same time, the preserved expression of other ligands, mainly perforin and granzyme B, allows DCs from glioblastoma patients to lyse tumor cells, although at a lower level compared to the donor IFN-DCs." (PMID 32326230, 2020). "Pan-cancer analysis also showed higher GZMB mRNA expression in many cancers (compared to normal tissues), such as cholangiocarcinoma, glioblastoma multiforme, kidney renal clear cell carcinoma, gastric adenocarcinoma, as well as head and neck squamous cell carcinoma." (PMID 40766321, 2025). "In addition, dsDNA and rIL-2 stimulated the expression of perforin and granzyme B (in the presence of dsDNA), suggesting the possibility of enhancing DC cytotoxicity against autologous glioblastoma cells via various mechanisms." (PMID 32326230, 2020). "The findings suggest that Talpha1 enhancesBCNUmediated eradication of glioblastoma in vivo, and that Talpha1mediates its effects by activating pro-apoptosis mechanisms,rendering neoplastic cells more sensitive to oxidative stress andimmune-mediated killing by Granzyme B and chemotherapeutic agents." (PMID 20111737, 2009). "Glioblastoma multiforme (GBM) also showed elevated GZMB expression." (PMID 40766321, 2025). "Regarding its function, TCC88 showed in vitro cytotoxicity against an autologous glioblastoma cell line and a multifunctional pro-inflammatory phenotype with strong secretion of TNF, IFNγ, granzyme B, GM-CSF and others." (PMID 37198490, 2023). "Conversely, higher expression levels of GSDMB, GZMA, and GZMB were detected in T cells, whereas NLR4 and CASP5 showed specifically high expression levels in TAMs, and CASP5, GZMA, GZMB, and NLRC4 were barely detected in glioblastoma cells." (PMID 35990696, 2022). "Thus, IFN-DCs from glioblastoma patients were comparable with donor IFN-DCs in terms of certain intracellular molecule expression in cytolytic granules, such as perforin, granzyme B, CD107a, as well as surface molecules FasL and TRAIL." (PMID 32326230, 2020). "In glioblastoma mice models, TEXs from glioblastoma GL26 cell line reduced the percentages of CD8+ T cells and inhibited the activation of CD8+ T cells, inducing decreased release of IFN-γ and granzyme B." (PMID 28642882, 2017). "To study the potential role of Talpha1 in enhancing T cell-mediated killing of 9L glioblastoma cells, we constructed an in vitro assay in which Talpha1- or vehicle-treated 9L cells were incubated with Granzyme B in the presence or absence of Streptolysin O (permeabilizing agent) for 1 or 3 hours." (PMID 20111737, 2009).
prostate carcinoma (19 papers, 2013 to 2024). A carcinoma that arises from epithelial cells of the prostate gland. "Another mechanism that sensitizes prostate cancer cells to ionizing radiation is the activity of the perforin and granzyme B proteins, which are an important element of the killer properties of lymphocytes and NK cells." (PMID 36142554, 2022). "Inhibiting granzyme B by its natural inhibitor serpin B9 (PI-9) was reported to protect prostate cancer cells from natural killer cell-induced apoptosis." (PMID 34944392, 2021). "Previous study indicates that deletion of exosomal PD-L1 results in significantly decrease percentage of Tim3+ cells and increased Granzyme B T cells in mouse prostate cancer models." (PMID 32391259, 2020). "For the first time in prostate cancer, GZMB was detected in ARCaP-M secretions and found to enhanced invasion." (PMID 32764784, 2020). "For the first time in human prostate cancer, we identify GZMB secretion by ARCaP-M and its potential role in increasing cancer invasion." (PMID 32764784, 2020). "This study reports that GZMB secretion by mesenchymal-like androgen-repressed human prostate cancer cells promotes invasion, suggesting a possible extracellular role for GZMB in addition to its classic role in immune cell-mediated cytotoxicity." (PMID 32764784, 2020). "We measured the secretion of granzyme B stimulated by the NK cell-prostate cancer cell interaction using an assay of the protease activity of granzyme B in the co-culture supernatant." (PMID 23165940, 2013). "However, studies on GzmB-induced radiosensitization in lung cancer and prostate cancer, respectively, are interesting." (PMID 38264648, 2023). "In the spontaneous TRAMP model of prostate cancer, expression of a dominant-negative form of TGFβ receptor II in T cells exhibited tumor protection that was associated with enhanced CD8+ T cell infiltration and Granzyme B expression." (PMID 34789823, 2021). "We then questioned whether C2GnT expression by prostate cancer cells affects the cytotoxic activity of NK cells, since the interaction of NK cells with C2GnT-expressing prostate cancer cells was impaired and the secretion of the target cell apoptosis-inducing substance, granzyme B was reduced." (PMID 23165940, 2013). "In this study, we describe a strategy to reengineer the pro-apoptotic proteases Granzyme B (GZMB) and Trypsin for activation by PSA within the prostate cancer ECF." (PMID 29854290, 2018). "Numbers of granzyme B+ cells showed a similar trend, with significantly higher numbers in PIN (4.9 ± 2.42), compared to advanced (2.6 ± 1.67) and evanescent prostate carcinoma (2.83 ± 1.85, p = 0.0149)." (PMID 28567040, 2017). "Although GZMB extracellular secretion by prostate cancer cells has not been previously reported, it was detected in our late-stage androgen-repressed prostate cancer, ARCaP-M, CM." (PMID 32764784, 2020). "In patients with prostate cancer, MDSCs accumulate in the blood as prostate cancer progresses and inhibit the proliferation of autologous CD8+ T cells and the production of interferon-γ (IFN-γ) and granzyme-B." (PMID 30736371, 2019). "Finally, the disruption of the IL6R/STAT-3 axis in prostate cancer cells and the blocking of TIGIT on NK-92 were observed to increase the cytotoxicity of NK-92 cells against DU145 cells through an increase in sFasL, granzyme A, granzyme B, and granulysin." (PMID 35465350, 2022). "Likewise, we determined that using these treatments in combination with anti-TIGIT increases and maintains the expression of some factors such as NKp46 and secretion of granzyme A, granzyme B, perforin, and granulysin which may regulate cytotoxicity against DU145 prostate cancer cells." (PMID 35465350, 2022).